IL1B (interleukin 1 beta)
Diseases named in the same sentence as IL1B in open-access papers (continued):
Sharing a sentence is not in itself a finding about the gene and the disease.
psoriasis (continued). "The values of IL-1β, sialic acid, and Siglec-14 after treatment in healthy subjects were statistically significantly higher than in psoriasis patients." (PMID 41598424, 2026). "Our analysis identified CASP1, CASP5, AIM2, NOD2, GZMB, GZMA, and IL1B as key hub genes in the inflammatory pathways driving psoriasis pathogenesis." (PMID 40771724, 2025). "CLDNs are integral to both Th2 and IL-1β inflammatory pathways in the context of psoriasis–AD overlap." (PMID 39859462, 2025). "The NLRP3 inflammatory corpuscle is an important inflammatory regulator that can promote the maturation and release of proinflammatory cytokines, such as IL-1β, after activation, thus aggravating the inflammatory state of psoriasis." (PMID 40430037, 2025). "We thus blocked the proinflammatory cytokines TNF-α, IL-6, IL-1β, and IL-23A, which are known to be crucial to γδ T cell activation, in WT and Acvr1b-Lyz2cre mice during psoriasis." (PMID 40067393, 2025). "CASP1 has long been recognized as a central mediator of IL-1β and IL-18 processing, two cytokines that contribute to the chronic inflammation in psoriasis." (PMID 40771724, 2025). "Pyroptosis is a highly inflammatory process that leads to the release of pro-inflammatory cytokines like IL-1β and IL-18, which are known to contribute to the chronic inflammation observed in psoriasis." (PMID 40771724, 2025). "Here, it was observed that the cytokines IL‐1β and IL‐8 were significantly increased in new‐onset psoriasis." (PMID 40181552, 2025). "Several interleukins including IL-17A, IL-22, IL-23, IL-36γ, IL-6, and IL-1β have emerged as the potential biomarkers of subclinical inflammation and treatment resistance in psoriasis." (PMID 40731810, 2025). "Results showed that IFN-γ, TNF-α, IL-1β, IL-6, IL-17A, IL-18, and IL-23 in psoriasis patients had significantly higher levels compared to controls and a strong correlation between PASI scores and these cytokines." (PMID 40699767, 2025). "DCs in the skin release proinflammatory cytokines such as tumor necrosis factor-alpha (TNF-α), interleukin 23 (IL-23), IL-6, and IL-1b as psoriasis spreads." (PMID 38712377, 2025). "It is widely believed that the ratio of IL1α or IL1β to IL1Ra is a contributing or determining factor in inflammatory diseases, such as polymorphic light eruption, psoriasis and AD 64,72,73." (PMID 39975900, 2025). "Recent evidence has also reported significant increases in IL-6 and IL-1β across different severities of psoriasis, as measured by PASI and BSA scores." (PMID 40004904, 2025). "Some studies investigated the presence of several disease-specific inflammatory cytokines such as TNF, IL-1β, IL-17A, IL-23, and other cytokines in patients with psoriasis, which were elevated compared to controls." (PMID 39775226, 2025). "ELISA further confirmed that PSVII reduced the levels of IL-1β and IL-18 in the peripheral blood of psoriasis mice." (PMID 40405066, 2025). "Upon activation, both AIM2 and NOD2 trigger the formation of inflammasomes that ultimately lead to CASP1 activation, which processes pro-inflammatory cytokines such as IL-1β, which is also a key player in psoriasis through our former analysis." (PMID 40771724, 2025). "In psoriasis, a chronic inflammatory skin disease, IL-1β and IL-18 are increased, and excessive NLRP3 and caspase-1 expression levels are associated with its development." (PMID 39684233, 2024). "TNF‐α, IL‐1β, IL‐23, IL‐17, IL‐22, Cox2, and iNOS are all inflammatory cytokines involved in the pathogenesis of psoriasis, and CXCL1, CXCL8, and CCL20 are antimicrobial peptides and chemokines produced by keratinocytes." (PMID 38967379, 2024).
psoriasis (continued). "In psoriasis patients with H. pylori infections, the Psoriasis Area and Severity Index (PASI) scores were higher, so were the mucosal levels of psoriasis-associated cytokines IL-1β, IL-6, IL-8, and TNF-α." (PMID 38347543, 2024). "A strong upregulation of Casp1 and Il1b expression was also found in the IMQ-induced psoriasis mouse model." (PMID 39352743, 2024). "Mice were systemically administered anti-IL-1R1 antibody, which blocks the interaction of IL-1β with its cognate receptor IL-1R during the development of psoriasis." (PMID 38704587, 2024). "γδT cell activation through IL-1β has been shown critical for the disease development in IMQ-induced psoriasis model." (PMID 38348035, 2024). "Psoriasis involves abnormal cytokine proliferation and secretion from keratinocytes, with IL-1β playing a significant role in systemic immune responses." (PMID 39189252, 2024). "Gender distribution due to the hormonal impact on skin can further affect psoriasis course, as sex hormones, like estrogens, inhibit the production of psoriasis-related cytokines, like IL-1β and IL-23, by neutrophils and dendritic cells, respectively." (PMID 38400161, 2024). "The target proteins of these active compounds, including IL1B, TNF, STAT3, IL6, NOS2, and NFKBIA, were found to be directly associated with psoriasis-related disease proteins." (PMID 39590306, 2024). "In psoriasis, pathogenic T cells activate the NLRP3 inflammasome in keratinocytes, leading to the cleavage of pro-IL-1β by caspase-1 and the production of active IL-1β, which exacerbates skin inflammation." (PMID 38892253, 2024). "Knockout of GSDMD in vivo is effective in significantly ameliorating IMQ-induced psoriasis-like lesions and reducing the level of skin inflammation, which also notably reduces the expression of the pyroptosis-inducing inflammatory cytokine IL-1β." (PMID 39717896, 2024). "Estradiol can inhibit the production of IL-1β by macrophages, and IL-1β is necessary for the generation of IL-17A in the psoriasis model." (PMID 39703508, 2024). "These cells, under the influence of IL-1β and IL-23 stimulation, produce -IL-17 and IL-22, which in turn constitute an important element in the pathogenesis and development of psoriasis." (PMID 39063202, 2024). "In sum, this study proposes a protective role of myeloid autophagy in the pathogenesis of psoriasis via limiting IL-1β-dependent neutrophilic inflammation." (PMID 38704587, 2024). "Due to the inhibitory effect of estrogens on the production of psoriasis-related cytokines, like IL-1β and IL-23, by neutrophils and dendritic cells, the conclusion that female gender is protective was formed." (PMID 38400161, 2024). "Like in psoriasis, the IL-1β/IL-23/Th17 axis is thought to be the primary pathway of HS inflammation." (PMID 39337637, 2024). "A recent study highlighted the pivotal role of the IL-1β–IL-1R signalling pathway in psoriasis pathogenesis." (PMID 38704587, 2024). "IL-1β and IL-6 are commonly upregulated inflammatory cytokines during psoriasis and stimulation of keratinocytes with TLR agonists have been shown to induce their expression." (PMID 39586195, 2024). "It was reported that pro-inflammatory cytokines and mediators such as IL-17A, IL-22, IL-23, IL-6, IL-1β, and p65 play an important role in the development and maintenance of psoriasis." (PMID 39296901, 2024). "Researchers revealed that pro-inflammatory cytokines (IL-1β, IL-6, and IL-12) were significantly increased and anti-inflammatory cytokines (e.g., IL-10) were decreased in mice with psoriasis after sleep deprivation." (PMID 38347543, 2024). "Interactions between the neuropeptides and mast cells induces inflammation by causing mast cells to release inflammatory cytokines IL-1β and TNF-α, and it contributes to the complex pathogenesis of itch in psoriasis." (PMID 39337637, 2024). "Elevated levels of IL‐1β are often observed in inflammatory skin diseases such as psoriasis and eczema." (PMID 39031931, 2024).
psoriasis (continued). "Currently, the only available option for inhibiting NLRP3-mediated effectors in clinical practice in both HS and psoriasis is drugs targeting IL-1β, like anakinra and canakinumab." (PMID 38248345, 2024). "This inhibition resulted in a significant decrease in key inflammatory cytokines (Il1b, Il6, Il12b, Il17a, Il22, and Tnf) that are critical in psoriasis’ pathogenesis." (PMID 39335596, 2024). "IL-1β, a significant inflammatory cytokine of pyroptosis, has a crucial function in the pathogenesis of psoriasis." (PMID 39717896, 2024). "α-humulene from Pini koraiensis semen was found to interact with psoriasis-related proteins such as IL1B and TNF, which play crucial roles in inducing inflammatory cytokines and amplifying immune responses." (PMID 39590306, 2024). "In turn, pro-inflammatory cytokines such as TNF-α, IL-1β, and IL-6, which are increased in psoriasis, can activate LOX-1, promoting the uptake of ox-LDL by macrophages." (PMID 37234169, 2023). "Remarkably, IL-4 is a negative regulator of Th1 and Th17 cells, which can inhibit the secretion of IL-1b and IL-6 by psoriasis epidermal cells." (PMID 37408052, 2023). "The use of drugs that inhibit NLRP3 and/or caspase-1 activation, such as metformin and ginsenoside Rg1, has shown a positive effect in the treatment of psoriasis-like lesions by inhibiting Il1b and keratinocyte proliferation." (PMID 37564649, 2023). "For example, in psoriasis-a chronic autoimmune-mediated inflammatory skin disease-cytosolic DNA induces IL-1β release from keratinocytes via an AIM2-dependent inflammasome." (PMID 36680007, 2023). "In a mouse model of psoriasis induced by imiquimod, the extract reduces psoriasis-related inflammation, including caspase-1 activation, IL-1β maturation, IL-17 production, and overall disease severity." (PMID 37836436, 2023). "In agreement with our study, psoriatic skin-treated with ScF had a significantly low levels of mTOR protein alongside the downregulation of TNF-α, IL-1β, and IL-17 indicating an inhibitory effect of ScF on mTOR signaling to mitigate psoriasis severity." (PMID 37495626, 2023). "IL-1β is a key pro-inflammatory marker within the skin, which is often upregulated in chronic inflammatory conditions such as psoriasis, and can work in synergy with other inflammatory markers, such as Tnfα, to amplify the response." (PMID 37299497, 2023). "An ascorbic acid derivative has been shown to ameliorate imiquimod-induced psoriasis-like dermatitis by suppressing inflammatory cytokine (IL-1β and TNF-α)." (PMID 37492568, 2023). "Conversely, the overexpressed IL-17 cytokine in psoriasis leads to the activation of the NF-ᴋB pathway and the production of other proinflammatory cytokines-IL-1β, IL-6, and TNF-α." (PMID 38003284, 2023). "IL-1β has been suggested to contribute to numerous skin inflammatory diseases, such as AD and psoriasis." (PMID 37569742, 2023). "The recruitment of circulating leukocytes to the epidermis and the production of pro-inflammatory factors, such as TNF-α, IFN-γ, IL-6, IL-8, IL-23, IL-1β, and IL-17A play a crucial role in the development of psoriasis." (PMID 37346040, 2023). "Corresponding with findings of lesional skin, peripheral blood levels of ASC, IL-1β and IL-18 were found increased in untreated psoriasis patients compared to healthy controls." (PMID 37325658, 2023). "Upregulation of the activation of inflammasome and production of IL-1β have been reported in patients with psoriasis." (PMID 37964882, 2023). "Patients with psoriasis present relatively high plasma levels of inflammasome-generated IL-1β and high expression of inflammasome components such as NLRP3, NLRP1, and absent in melanoma 2 (AIM2)." (PMID 37964882, 2023). "Then, to investigate the mechanism of TGF-β induction, we stimulated healthy keratinocytes (NHEK) in vitro with a number of cytokines characterizing the psoriasis microenvironment including IL-1β, IL-6, IL-17A, IL-19, IL-22, IL-23, IL-26, and IFN-γ." (PMID 37391412, 2023).
psoriasis (continued). "When keratinocytes are infiltrated with proinflammatory cytokines such as IFN-γ and TNF-α, AIM2 inflammasome activation and downstream IL-1β release have been proven to result in psoriasis lesions." (PMID 36742336, 2023). "This correlation mirrors findings in psoriasis, a condition where IL-1β is known to play a pivotal role in initiating inflammation." (PMID 37965323, 2023). "TNF‐α, as well as IL‐1β, induced keratinocyte activation plays a pivotal role in the pathogenesis of many inflammatory skin diseases, such as psoriasis, and different inhibitors of these cytokines have been proven to be a promising treatment in such diseases." (PMID 36544622, 2023). "Cytokines that upregulated in psoriasis patients include TNF-α, IL-1β, IL-12, and IL-17A were also involved in the development of lung cancer, indicating that both psoriasis and lung cancer are closely involved with immune alteration." (PMID 36604675, 2023). "IL-1β, which is secreted by macrophages and has a vital role in psoriasis immunity, and IL-6, which activates the JAK-STAT pathway and exhibits elevated levels in psoriasis patients’ lesions, were both significantly increased in psoriasis-induced mice." (PMID 38007430, 2023). "CCL5 has been implicated in the progression of scleroderma, while IL-1β and CXCL10 have been proposed as biomarkers of disease progression in psoriasis." (PMID 37228128, 2023). "In psoriasis, the significant elevation of IL-1β mRNA and its protein expression level has been observed in the affected skin of psoriasis patients." (PMID 35203707, 2022). "We found that psoriasis-related cytokines, namely IL-17, IL-22, IL-1β, and TNF-α, reduced CAV-1 expression in human keratinocytes." (PMID 36532050, 2022). "Whereas most research focused on one or two PRGs in vivo or vitro, for instance, the pathogenesis of psoriasis is closely related to caspase-1, IL-1β, IL-18, or GSDMD." (PMID 36110207, 2022). "IL-1β plays an important role in the pathogenesis of psoriasis, IL-1β is known to be critical in IL-17-producing T cell differentiation and activation." (PMID 35693833, 2022). "Other proinflammatory cytokines, including IFN-γ, TNF-α, IL-1β, IL-6, IL-22, IL-26, IL-29, or IL-36, have also been reported to play important roles in the development of psoriasis." (PMID 35313642, 2022). "The expression of CTACK would be upregulated with the stimulation of TNF-α and IL-1β and be reduced cutaneously during the administration of etanercept in psoriasis patients." (PMID 36741410, 2022). "IL-1β blocks insulin-dependent differentiation of keratinocytes and drives keratinocyte proliferation, both of which are hallmarks of psoriasis pathogenesis." (PMID 34816303, 2022). "Inflammation-related factors such as TNF, IL6, and IL1β were abnormal throughout the pathogenesis of psoriasis." (PMID 35265149, 2022). "Over the past two decades, inflammatory circuit triggered by various cytokines (e.g., IFN-γ, TNF-α, and IL-1β) have been found to play an important role in regulating the development and progression of psoriasis." (PMID 36618400, 2022). "In line with that, we detected significantly lower IL-1β production in pDCs of psoriasis patients with elevated IFN-α levels." (PMID 36293012, 2022). "In vitro, estrogens suppress the production of psoriasis-related cytokines such as IL-1β and IL-23 from neutrophils and dendritic cells, respectively." (PMID 36013129, 2022). "25-hydroxy vitamin D downregulates the expression and production of several pro-inflammatory cytokines including TNF-α, IL-1β, IL-6, and IL-8, thereby establishing its anti-inflammatory effect on the inflammatory profile of psoriasis." (PMID 36261848, 2022). "Among them, the p38 MAPK signaling pathway is the most closely related to the development of progression of psoriasis, which can promote the secretion of inflammatory cytokines (e.g, IL-6, IL-1β, and TNF-α) to accelerate the progression of psoriasis." (PMID 36618400, 2022).
psoriasis (continued). "In imiquimod-induced mouse psoriasis, andrographolide inhibited the generation of proinflammatory cytokines such as IL-23 and IL-1b and induced the autophagic proteolysis of MyD88, which controlled MyD88-dependent cytokine activation and alleviated psoriasis." (PMID 36238575, 2022). "Analysis of the inflammatory factors in the serum showed that the levels of TNF-α, IL-6, IL-1β, and IL-17 were significantly higher in psoriasis patients than in HCs." (PMID 35927231, 2022). "In summary, we demonstrated that PUN alleviates psoriasis by suppressing excessive IL-1β expression and secretion." (PMID 35153790, 2022). "Significantly higher levels of IFN-α and pro-inflammatory cytokines, including IL-1β, were measured in serum samples from patients with psoriasis compared to healthy donors." (PMID 36293012, 2022). "In psoriasis, keratinocytes regulate differentiation and activation of Th17 and Th22 cells by producing IL-1β and IL-6." (PMID 35069008, 2022). "We found that PUN can relieve psoriasis-like symptoms by suppressing the nuclear factor kappa B (NF-κB)-mediated IL-1β transcription and caspase-1-regulated IL-1β secretion in vivo and in vitro." (PMID 35153790, 2022). "Although most psoriasis-related researches have mainly focused on the interleukin-23 (IL-23)/interleukin-17 (IL-17) axis, emerging evidence indicates that interleukin-1β (IL-1β) also plays a critical role in psoriasis." (PMID 35153790, 2022). "Here, we gave the first evidence that PUN can alleviate the severity of psoriasis by downregulating IL-1β expression and subsequent IL-1β-mediated inflammatory responses in vitro and in vivo." (PMID 35153790, 2022). "Cultured primary keratinocytes treated with the ferroptotic inducer erastin had reduced viability and increased expression of a suite of psoriasis-associated cytokines (TNF-α, IL-6, IL-1α, IL-1β, IL-17, IL-22, and IL-23)." (PMID 35929827, 2022). "Coptisine also lowered the levels of inflammatory cytokines TNF-α and IL-1β in the prefrontal cortex of psoriasis mice." (PMID 35209199, 2022). "A recent study integrating flow cytometry and scRNA‐seq with published skin data sets examined the Mφ and DC landscape in AD and psoriasis and identified IL‐1B and IL‐23 producing CD14+ DC3s as potential inflammatory modulators in psoriasis." (PMID 35196402, 2022). "The serum levels of pro-inflammatory cytokines such as IFN-7, TNF-α, IL-1β, IL-6, IL-8, and IL-17 significantly decreased in patients with psoriasis after a three-month administration of vitamin D supplement." (PMID 36558443, 2022). "In the current study, elevated levels of proinflammatory molecules TNF-α and IL-1β were observed in the prefrontal cortex of IMQ-induced psoriasis mice." (PMID 35209199, 2022). "Previous studies demonstrated the key pathogenetic role of IL-1β in aggravating psoriatic inflammatory cascade and recalling psoriasis recurrent-related inflammatory memory." (PMID 35153790, 2022). "AIM2 response to dsDNA and then induce AIM2-dependent release of IL-18 and IL-1β, which plays a critical role as a trigger of autoimmune diseases, including psoriasis, systemic lupus erythematosus, primary Sjogren’s syndrome." (PMID 36118867, 2022). "Accumulating evidence demonstrates the role of NLRP3 in psoriasis patients, with potential reductions in disease activity and fatigue from mediating pro-inflammatory cytokines (e.g., IL-1β and TNF-alpha) regulated by the NLRP3 inflammasome." (PMID 35663672, 2022). "We found that the mRNA and pro-/mature protein levels of IL-1β, another important cytokine in psoriasis, were significantly increased after stimulation with IL-17A and TNF-α." (PMID 35153790, 2022). "The cytokine IL-1β was also involved in the skin inflammation of psoriasis via IL-1β-IL-1R Signaling Pathway." (PMID 35213665, 2022).